CD4 (CD4 molecule)
Diseases named in the same sentence as CD4 in open-access papers (continued):
Sharing a sentence is not in itself a finding about the gene and the disease.
seborrheic dermatitis (10 papers, 2009 to 2025). A chronic, inflammatory skin disorder that affects the scalp, central face and skin folds; it is characterized by scaling and itching. "It has also been shown that seborrhoeic dermatitis generally occurs in individuals with CD4 cell counts between 201–500 cells/mmc." (PMID 24112129, 2013). "This high rate could be explained by the number of CD4 cells present in the patients, as in the seborrheic dermatitis patients, 24 had <500 CD4 cells including nine with <200 CD4 cells." (PMID 34682276, 2021). "Seborrheic dermatitis is frequently observed in patients with HIV infection, particularly in those with profound CD4 T cell depletion." (PMID 41035583, 2025). "A Korean case series further demonstrated that conditions such as seborrheic dermatitis, irritant contact dermatitis, pruritus, and folliculitis occur significantly more frequently in HIV patients with CD4-positive T cell counts below 200×106/L." (PMID 41035583, 2025).
T lymphocyte deficiency (10 papers, 2012 to 2025). "The parameters of immune status in children with UBA are characterized by T-lymphocytes deficiency, lower counts of CD4+ cells and lower CD4+/CD8+ ratio." (PMID 23984295, 2013). "This contrasts with PJP patients suffering from T-lymphocyte deficiency, particularly CD4+ T-lymphocytopenia, characterized by compromised macrophage function and adherence of alveolar epithelium, which obstructs gas exchange and significantly impacts host prognosis." (PMID 41070051, 2025). "Additionally, stage 3 of CD4 T-lymphocyte deficiency, the higher viral load, and treatment duration are risk factors influencing the appearance of virus mutations." (PMID 40864119, 2025). "Nude mice, characterized by their thymic aplasia, are unable to produce functional CD4+ and CD8+ T lymphocytes, which play important roles in clearing MV from the central nervous system." (PMID 23134812, 2012).
abdominal aortic aneurysm (9 papers, 2014 to 2025). Enlargement and ballooning of the vessel that supplies arterial blood to the abdomen, pelvis and legs. "Researchers also found that various proinflammatory factors in patients with abdominal aortic aneurysms cause an imbalance of CD4+ T cells and upregulate the expression of AIM2 in them." (PMID 36742336, 2023). "CD4+CD25+ regulatory T cells (Tregs) have been shown to protect against the development of abdominal aortic aneurysm (AAA)." (PMID 31328426, 2019). "The mediators produced by CD4+ T lymphocytes are involved in the pathogenesis of aneurysmal lesions in abdominal aortic aneurysm (AAA) patients." (PMID 30686933, 2018). "GRK2 expression positively correlates with myeloid- (CD68) and lymphoid-specific (CD3, CD4, and CD8) markers and with leptin in PVAT from patients with abdominal aortic aneurysms." (PMID 33020373, 2020). "CD4+ T cells and CD8+ T cells showed distinct transition trajectories and subsets and displayed different immune and transcriptional states in thoracic and abdominal aortic aneurysm samples." (PMID 36703732, 2022).
age (9 papers, 2012 to 2025). A temporal measurement of the time period elapsed since an identifiable point in the life cycle of an organism. "We have previously shown that lower naïve CD4+ T cells are a biomarker for an age-related immune phenotype (ARIP) and are associated with an increased risk of age-related morbidity and mortality." (PMID 38999941, 2024). "The result of the ROC curve analysis of CD4+ T lymphocytes and the CD4/CD8 ratio ranged between 0.6 and 0.7, indicating a relatively high diagnostic value of T lymphocytes for clinical prognosis in age-related vascular inflammation." (PMID 36362055, 2022). "We have shown that sTg mice, which develop an age-related photoreceptor degeneration with reduced levels of HEL expression, become less susceptible to HEL-activated 3A9 CD4+ T cell-induced EAU." (PMID 33013877, 2020). "This will lead to an inversed CD4/CD8 T cell ratio, and a low CD4/CD8 T cell ratio has been recognized as a biomarker of an age-related increase in mortality." (PMID 32260178, 2020). "Another recently identified subset of age-related CD4+ T cells are cytotoxic CD4+ T cells, characterized by the expression of Eomes and Gzmk, and the release of proinflammatory cytokines (interferon γ [IFN-γ] and TNF-α) and cytotoxic factors (GZMB and perforin)." (PMID 40443365, 2025).
airway allergy (9 papers, 2010 to 2023). "We believe that the complex formations of livin/GATA3 enhances the stability of livin expression that triggers the high expression of IL-4 by activating the transcription of IL4 gene and facilitates CD4+ T cells to differentiate into Th2 cells, and causes airway allergy." (PMID 35717553, 2022). "Cutaneous allergen exposure can lead to airway allergy to the same allergen via the induction of Th2 memory CD4 T cells by skin DC, a phenomenon referred to as ‘atopic march’." (PMID 37190854, 2023). "The inhibition of either Etr or RhoA, or the depletion of XBP1 in CD4+ T cells, prevented the induction of airway allergy using the MNP.Derf1 protocol." (PMID 35910793, 2022). "Livin increases the expression of IL-4 and facilitates naive CD4+ T cells to differentiate into Th2 cells, which triggers airway allergy." (PMID 35717553, 2022). "In conclusion, AR patients with airway allergies had decreased numbers of CD4+CD25+ and CD4+CD25hi TRegs, and the number of Treg cells was correlated negatively with total serum IgE levels." (PMID 31826046, 2018). "Intraperitoneal allergen sensitization followed by localized airway challenge is a well-established CD4+ T-cell–dependent model of airway allergy." (PMID 27484038, 2017). "An intriguing feature of our earlier study was that, in the C57BL/6 strain, CD4− MLNC were also able to transfer significant protection against airway allergy." (PMID 20306466, 2010). "This study identified a new therapeutic target, XBP1 in CD4+ T cells, for airway allergy." (PMID 35910793, 2022). "In previous studies, our group used lentivirus-mediated RNAi and co-immunoprecipitation had clarified survivin had positive regulation on the expression of IL-4 in CD4 + T cells, and confirmed that survivin plays a critical role in the pathogenesis of airway allergy." (PMID 35717553, 2022). "It is reported that the expression level of GATA3 in CD4+ T cells of AAD mice was significantly increased compared with that of naïve mice, which suggests that GATA3 is involved in the development of airway allergy." (PMID 35717553, 2022). "Notably, Treg cell paucity together with elevated precursor frequencies of allergen-specific CD4+ effector T cells induced herein by TCR transgenesis, are both highly reminiscent of the constellation found in human individuals suffering from respiratory allergies." (PMID 29678672, 2018). "Although the Treg (CD4+CD25+Foxp3+) is a central player in the immunoregulatory network, in the contexts of both airway allergy and autoimmune disease, this is not the only cell population capable of down-regulating immune responsiveness." (PMID 20306466, 2010).
anaphylaxis (9 papers, 2013 to 2025). An acute hypersensitivity reaction that occurs from exposure to an allergen. "We demonstrate that tBHQ in diet greatly increases allergen sensitization and exacerbates anaphylaxis and this effect is dependent on expression of Nrf2 in CD4+ T cells." (PMID 40115160, 2024). "To investigate the role of Nrf2 in the effect of tBHQ on OVA-induced anaphylaxis, we implemented adoptive transfers of CD4+ T cells from wild-type or Nrf2-null mice and B cells from wild-type mice into SCID mice." (PMID 40115160, 2024). "In this study, we observed specific immune cell subsets, including macrophages, dendritic cells, CD8+ T cells, and CD4+ naïve T cells, which act in both anaphylaxis and STEMI." (PMID 37469874, 2023). "CD4+ Th2 responses are required for the development of IgE-MC-dependent food-induced anaphylaxis and CD4+ Th2 cell levels do positively correlate with food allergen-induced MC activation (MCPT-1) (r = 0.57, p < 0.05)." (PMID 31369572, 2019). "We document that MHC class-II restricted CD4+CD25+Foxp3+ Treg play a protective role in IgE-mediated systemic anaphylaxis in mice." (PMID 23922690, 2013). "After taking the intersection and excluding the immune cells with opposite infiltration trends in anaphylactic and STEMI groups, M0 macrophages, activated dendritic cells, CD4+ naïve T cells, and CD8+ T cells were identified as immune effector cells associated with both anaphylaxis and STEMI." (PMID 37469874, 2023). "In particular, oral supplementation with B. coagulans 09.712 and L. plantarum 08.923 significantly ameliorates anaphylaxis symptoms and increases the population of CD4+ CD25+FoxP3+ T cells through mTORC inhibition, FoxP3 upregulation, and GATA-3 downregulation." (PMID 30828329, 2019). "Upon adoptive transfer into OVA sensitized BLAB/c mice the CD4+ OVA-BAR-Tregs did not result in anaphylaxis, in response to the OVA contained in the BAR construct." (PMID 33854514, 2021).
bacterial vaginosis (9 papers, 2011 to 2023). Infection caused by bacterial overgrowth in the vagina. "In a model adjusted for a combined indicator of HIV status and CD4 group, bacterial vaginosis at the preceding visit was significantly associated with 24% increased odds for incident HPV among all HERS women (aOR = 1.24, 95% CI: 1.04, 1.47)." (PMID 21869857, 2011). "In a model adjusted for a combined indicator of HIV status and CD4 group, bacterial vaginosis was significantly associated with increased odds for prevalent HPV among all HERS women (aOR = 1.14, 95% CI: 1.04, 1.26)." (PMID 21869857, 2011). "For instance, HSV-2 (herpes simplex virus 2), Haemophilus ducreyi and bacterial vaginosis (BV) cause an increase in the number of CCR5+, activated and α4β7+ integrin CD4+ T-cells in FGT, thereby enhancing HIV susceptibility." (PMID 33013878, 2020). "The disease is more persistent among HIV-infected women with lower CD4 cell counts who are also more likely to develop more severe symptoms of bacterial vaginosis." (PMID 25313360, 2014). "Increased presence of bacterial vaginosis and anaerobes at low CD4 counts is a feature of HIV, and these conditions may alter the ability of GBS to colonize the vagina." (PMID 22000375, 2011). "On the other hand, coinfection of CD4 T-cells by HIV and HSV results in a rapid unidirectional replication of HIV, whereas the acquisition, reactivation, and shedding of HSV-2 are facilitated by disturbances in the vaginal flora resulting in bacterial vaginosis." (PMID 25313360, 2014).
chronic rhinosinusitis (9 papers, 2009 to 2024). Chronic form of sinusitis. "In the 0 to 5 years and 11 months age group children with chronic rhinosinusitis had serum CD4+ T lymphocyte counts on average 65.4 ±58 x 10-9cell/L below the count of children without rhinosinusitis (p = 0.002)." (PMID 19488563, 2009). "Thus, mucocele of the sinuses should be an expected entity in newly diagnosed HIV individuals on antiretrovirals with prior low CD4 counts (< 100 cells/mm3) with chronic rhinosinusitis." (PMID 39278063, 2024). "Children with chronic rhinosinusitis in both age groups had lower serum CD4+ T lymphocyte counts compared to those without chronic rhinosinusitis." (PMID 19488563, 2009).
Ebola (9 papers, 2016 to 2025). "Furthermore, depletion of CD8 and CD4 T cells resulted in loss of early control of virus replication, viremia and fatal Ebola virus disease (EVD)." (PMID 28256637, 2017). "An immunological signature in Ebola fatalities has been proposed, showing a massive CD4 and CD8 T-cell activation and an exhaustion of adaptive immune response." (PMID 28558022, 2017). "The prolonged two-phase study to monitor the effectiveness of Ebola vaccine for the respirational and sublingual (SL) adenovirus in non-human primates revealed durable protection from a single dose in monkeys with diverse Ebola GP-specific CD4+ T cells generation, and was an unstable approach." (PMID 36851146, 2023). "However, significant activation of B cells, DCs, CD4 and CD8 T cells for HIV and Ebola, suggested a strong immune response, albeit possibly insufficient for protection from infection." (PMID 38260393, 2025). "In addition, one study which compared survivors with PES to survivors without sequelae found had an increased CD8+ T-cell and CD4+ T-cell expression of IFNγ and TNFα following stimulation with Ebola antigens." (PMID 40561148, 2025).
End Stage Liver Disease (9 papers, 2011 to 2024). Final stage of a liver disease when the liver failure is irreversible and LIVER TRANSPLANTATION is needed. "We also detected the presence of CD4+CD3+ T cells in hepatocytes in vivo in explants from patients with end-stage liver diseases." (PMID 31693899, 2019). "This is shown by the fact that patients with BSI had lower CD4+ counts than the general population of PLWHIV and that, among them, mortality was higher in those with older age, more advanced CDC stage and comorbidities such as malignancies or end stage liver disease." (PMID 30931978, 2019).
Helicobacter infection (9 papers, 2012 to 2025). "Upon Helicobacter infection, CD4+ Trm cells orchestrate a swift recall response with the recruitment of circulating antigen-specific Th1/Th17 cells to trigger a tissue-wide pathogen clearance." (PMID 31156652, 2019). "During Helicobacter pylori (H. pylori) infection CD4+ T cells in the gastric lamina propria are hyporesponsive and polarized by Th1/Th17 cell responses controlled by Treg cells." (PMID 25807464, 2015). "CD4+ T cells are known to play a pivotal role in the immune response directed against Helicobacter infection." (PMID 24147103, 2013). "Previous investigation has demonstrated that CD4+ T cells play a crucial role in effective immunity against Helicobacter pylori (H.pylori) infection." (PMID 23234363, 2012).
HIV encephalitis (9 papers, 2005 to 2025). "Two additional patients were diagnosed with HIV encephalitis with low CD4 counts and were immunosuppressed due to their viral illness." (PMID 39030965, 2024). "Both CD4+ and CD8+ T lymphocytes have been shown to accumulate in AIDS patients with HIV encephalitis along with the demonstration that brain CD8-CTL are HIV-specific and are associated with HIV encephalitis." (PMID 19951441, 2009). "However, this association of early decay differences with CD4 counts is at variance with a report by Eggers and colleagues who correlated slower CSF decay after therapy with the presence of ADC or HIV encephalitis." (PMID 16266436, 2005).
hypersplenism (9 papers, 2014 to 2024). Overactive functioning of the spleen, resulting in excessive destruction of blood cells. "They found that the splenic ratio of CD4+:CD8+ lymphocytes from these patients were higher compared to the control group (P = 0.06) whilst the ratio of FOXP3+:CD4+ was lower than the control group, implicating an increase in CD4+ T cell immune responses during hypersplenism." (PMID 28535799, 2017). "Nevertheless, hypersplenism could not be associated with the decrease in the percentage CD4+ T‐cell observed in our group of cirrhotic individuals (since leucopenia affects the absolute number of the different leucocytes but not the proportion of them)." (PMID 31536177, 2019). "Moreover, Guo and co-workers reported that T lymphocyte subsets (CD4+CD25+CD127 low/-Treg) and Foxp3 ratio was strongly increased in subjects affected by hypersplenism and PH." (PMID 24976841, 2014). "Therefore, in this study, splenectomized patients with VL and HIV infection were investigated to understand why the CD4+ count fails to recover in these patients, evaluating the importance of spleen mass for hypersplenism and immunological failure." (PMID 38491526, 2024).
invasive carcinoma (9 papers, 2019 to 2025). A carcinoma that is not confined to the epithelium, and has spread to the surrounding stroma. "In invasive carcinoma, infiltration of CD4+, CD8+, and FOXP3+ TIL showed an association with disease-specific survival (p = 0.015, p = 0.039, p = 0.069, respectively) albeit borderline significance for FOX3P3+ TIL." (PMID 33146829, 2021). "When comparing pure DCIS and invasive carcinoma in the whole group, the infiltration of CD4+, CD8+, and FOXP3+ TILs and the presence of PD-L1+ immune cells were significantly higher in invasive carcinoma compared to pure DCIS (all p < 0.001)." (PMID 32216826, 2020). "DCIS coexisting with invasive carcinoma harboured denser stromal infiltrates of all immune cells and checkpoint proteins apart from CD4+ cells." (PMID 32203210, 2020). "Interestingly, the two cases associated with an invasive carcinoma showed an increased rate of CD8+ cells and a decreased rate of CD4+ cells in the infiltrative component." (PMID 37086293, 2023). "Regression of human PV-associated genital lesions is accompanied by an effective cell-mediated CD4+ T cell-dominated Th1 response and failure to develop an effective cell-mediated response results in persistent infection and an increased probability of progression to invasive carcinoma." (PMID 31231361, 2019). "In pre-invasive carcinoma, infiltration of S100A8+ IC revealed weak positive correlations with infiltration of CD4+, CD8+, and FOXP3+ TIL and PD-L1+ IC (rho 0.209–0.281)." (PMID 33146829, 2021). "A well characterised DCIS cohort (n = 700) with long-term follow-up comprising pure DCIS (n = 508) and DCIS mixed with invasive carcinoma (IBC; n = 192) were stained immunohistochemically for CD20, CD3, CD4, CD8, FOXP3, PD1 and PDL1." (PMID 32203210, 2020). "As a whole, the infiltration of CD4+ TILs was higher than that of CD8+ TILs in pure DCIS (p < 0.001), whereas the reverse was true in invasive carcinoma with the CD8+ TILs being the dominant subset (p = 0.006)." (PMID 32216826, 2020). "While CD4+ T cells were more abundant than CD8+ T cells in pure DCIS, CD8+ T cells were dominant in invasive carcinoma, especially in HR-negative tumors." (PMID 32216826, 2020). "In invasive carcinoma, infiltration of S100A8+ IC showed a weak positive correlation with infiltration of CD4+ TIL (rho = 0.263) and a moderate positive correlation with infiltration of CD8+ and FOXP3+ TIL and PD-L1+ IC (rho = 0.474, 0.482 and 0.525, respectively)." (PMID 33146829, 2021). "We also compared the dominance of CD4+ versus CD8+ TILs in pure DCIS and invasive carcinoma." (PMID 32216826, 2020). "However, the reason why CD4+ TIL infiltration differs in DCIS but not in invasive carcinoma in relation to CXCL10 expression needs further investigation." (PMID 34504204, 2021). "CD4+, CD8+, and FOXP3+ TIL and PD-L1+ immune cell infiltration was significantly higher in invasive carcinoma compared to pure DCIS regardless of the HR status." (PMID 32216826, 2020).
lichen planus (9 papers, 2009 to 2025). A chronic, recurrent, pruritic inflammatory disorder of unknown etiology that affects the skin and mucus membranes. "A high CD8:CD4 ratio was seen in three patients (two spongiotic dermatitis and one lichen planus like keratosis)." (PMID 35054387, 2022). "On immunohistochemical examination there was predominance of CD8+ T lymphocytes at the junction with scattered CD4+ T lymphocytes, characteristic of lichen planus." (PMID 20062629, 2009). "Thus, the overactivation of cytotoxic CD8+ cells and uninhibited production of proinflammatory cytokines such as IL‐2, TNF‐α, and IFN‐γ by CD4+ T cells play an important role in the implication of Lichen planus." (PMID 40626171, 2025). "Therefore, NK cells may provide an early stimulatory signal for the mobilization of CD4 + and CD8 + T cells upon their arrival in lichen planus-inflamed areas." (PMID 38053160, 2023).